SPIN1 (spindlin 1)
Diseases named in the same sentence as SPIN1 in open-access papers (continued):
Sharing a sentence is not in itself a finding about the gene and the disease.
cancer (continued). "Moreover, functional assays revealed that overexpression of miR-381 repressed cancer cell proliferation and invasion, which recapitulated the impact of SPIN1 depletion." (PMID 34753384, 2021). "Because SPIN1 mediates PI3K/AKT signaling to promote apoptosis resistance in cancer cell lines, we performed real-time qRT-PCR to test whether SPIN1 or SPIN3 affected the downstream targets of that pathway." (PMID 30197756, 2018). "Therefore, we further searched some available genomic and gene expression database for SPIN1 expression in cancers." (PMID 29547122, 2018). "Thus, we suspect that these cancer-related pathways may also contribute to SPIN1-induced NSCLC progression and radioresistance." (PMID 39548064, 2024). "Therefore, the dysregulation of SPIN1 in cancer cells may disrupt the efficiency of DSB repair, leading to increased resistance to DNA-damaging drugs." (PMID 39090319, 2024). "The overexpression of SPIN1 in cancer cells enhanced its binding to H3K9me3 and persistently promoted the activation of ATM-mediated DNA repair in cancer cells exposed to DNA-damaging drugs." (PMID 39090319, 2024). "Spindlin1 (SPIN1), a protein highly expressed in several human cancers, has been correlated with tumorigenesis and development." (PMID 29743122, 2018). "Our findings suggest that acting, at least in part, through SPIN1 and SPIN3, PUM proteins contribute to a mechanism promoting normal human male germ cell apoptotic status and thus preventing cancer." (PMID 30197756, 2018). "Spindlin 1 (SPIN1) is a histone methylation reader contributing to the epigenetic regulation of many oncogenic pathways so it is not surprising that SPIN1 was found to be overexpressed in many cancers." (PMID 37055532, 2023). "Altogether, by acting as SPIN1 and SPIN3 repressors, PUM proteins may promote a normal human male germ cell apoptotic status and thus prevent cancer." (PMID 33401540, 2021). "Taken together, these results demonstrate that SPIN1 specifically binds to uL18, but not uL5 or uL14, in cancer cells." (PMID 29547122, 2018). "SPIN1 regulation might be 3′UTR-dependent in mice at the oocyte-embryo transition and in cancer cells involving miR-489." (PMID 30197756, 2018). "First, SPIN1 has been reported to execute its oncogenic potentials by activating Wnt and PI3K/Akt pathways, both of which are closely correlated with cancer progression." (PMID 29547122, 2018). "In conclusion, our results suggest that at least in part through SPIN1 and SPIN3, PUM proteins may work as part of a mechanism promoting normal germ cell apoptotic status and thus preventing cancer." (PMID 30197756, 2018). "Similarly, SPIN1 upregulated and SPIN3 downregulated CYCD1, which is a downstream target of the PI3K/AKT pathway and contributes to apoptosis resistance in cancer cell lines." (PMID 30197756, 2018). "Therefore, it is not surprising that Spindlin-1 is overexpressed in many types of human cancers and contributes to tumor cell growth, migration, and invasion." (PMID 40512144, 2025).
tumor (25 papers, 2015 to 2025). "The histone code reader Spindlin1 (SPIN1) has been implicated in tumorigenesis and tumor progression, however, the exact molecular mechanisms underlying these processes remain incompletely understood." (PMID 40567896, 2025). "Although SPIN1 has been implicated in tumorigenesis and tumor progression, the underlying molecular mechanisms remain inadequately elucidated." (PMID 40567896, 2025). "SPIN1, a histone methylation reader with diverse biological functions, has been implicated in tumor formation and growth." (PMID 39090319, 2024). "The histone code reader Spindlin1 (SPIN1) has been implicated in tumorigenesis and tumor growth, but the underlying molecular mechanisms remain poorly understood." (PMID 25749382, 2015). "In this study, we conducted a comprehensive analysis of the associations between SPIN1 expression and various factors, including tumor progression, clinical stage, immune microenvironment, drug sensitivity and epigenetic regulation in a cohort of 375 GC patients and 32 controls." (PMID 40567896, 2025). "More interestingly, the tumour size and weight in the sh-SPIN1 groups exposed to irradiation were substantially smaller than those in the scramble groups with irradiation, suggesting that SPIN1 knockdown rendered NSCLC cells more susceptible to irradiation in vivo." (PMID 39548064, 2024). "Our study examined the relationships between SPIN1 expression and various factors including tumor progression, clinical stage, survival status, immune microenvironment and drug sensitivity within the cohort of 375 GC patients and 32 controls." (PMID 40567896, 2025). "Knockdown of Spindlin-1 has been shown to suppress cell growth and proliferation in multiple tumor cell lines." (PMID 40512144, 2025). "Previously, we demonstrated that Spindlin 1 (SPIN1) was related to tumour initiation and progression." (PMID 39548064, 2024). "Our study suggests a new therapeutic strategy for blocking SPIN1’s binding to H3K9me3 to inhibit tumor growth and chemoresistance." (PMID 39090319, 2024). "Suppressing SPIN1 expression or inhibiting its activity with small molecules leads to the inhibition of tumor cell growth in vitro and in xenograft models." (PMID 38777743, 2024). "Our experiments revealed for the first time that depletion of SPIN1 increased the DNA damage level and suppressed DNA repair processes, ultimately rendering NSCLC cells and xenograft tumours more susceptible to irradiation." (PMID 39548064, 2024). "Taken together, these results indicate that the depletion of SPIN1 has the potential to enhance tumor chemosensitivity." (PMID 39090319, 2024). "This study reveals the mechanism of SPIN1 in promoting GC tumor growth and provides evidence that SPIN1 is a novel prognostic biomarker and a promising therapeutic target in GC." (PMID 32767629, 2020). "The results indicated that SPIN1 expression, tumor stage, LNM, and distant metastasis were significantly correlated with OS of GC patients, whereas only distant metastasis was an independent prognostic predictor for OS (P < 0.05)." (PMID 32767629, 2020). "Tumour cells in the galectin-1-rich environments express genes important for tumour progression such as SPIN1, FUSIP1, TRIM23, PTPLAD1, MAP3K2." (PMID 30925774, 2019). "In order to validate the miR-148/152–SPIN1–downstream effectors axis in vivo, we established an MCF-7/ADM derived xenograft tumor model, by suppressing SPIN1 expression." (PMID 29743122, 2018). "The oncogenic potential of SPIN1 was later supported by the observation that overexpression of SPIN1 increases transformation and tumor growth ability of NIH3T3 cells." (PMID 29547122, 2018). "This tumour suppressive role was mediated through targetting of SPIN1 effecting the downstream signaling of WNT/β-catenin and Akt." (PMID 30323900, 2018).
tumor (continued). "In line with the tumor growth curve, the reduction of tumor mass and weight by SPIN1 knockdown was more profound in HCT116p53+/+ groups (~60% reduction in weight) than that in HCT116p53-/- groups (~30% reduction in weight)." (PMID 29547122, 2018). "While several studies correlated increased expression of the histone code reader Spin1 with tumor formation or growth, little is known about physiological functions of the protein." (PMID 29168801, 2017). "Spindlin-1 is not only involved in the growth of tumor cells but may also play a role in the functioning of immune cells." (PMID 40512144, 2025). "Interestingly, suppression of SPIN1 expression by ShRNA‐SPIN1 lentiviral vector decreases tumor xenograft growth in vivo." (PMID 32767629, 2020). "The results demonstrated that lentiviral packaged ShRNA‐SPIN1 could inhibit GC tumor growth, which indicated that SPIN1 might be a promising target for GC therapeutics, and LV‐ShRNA‐SPIN1 gene therapy may be a promising novel approach to treat advanced GC." (PMID 32767629, 2020). "To further explore whether SPIN1 can be used as a target for GC therapy in vivo, we constructed xenograft tumor models." (PMID 32767629, 2020). "Furthermore, the results showed positive relationship between SPIN1 expression and pN classification (P = 0.035) and tumor stage (P = 0.020)." (PMID 29743122, 2018). "SPIN1 expression in cells is tightly controlled, as several studies have shown that SPIN1 expression could be negatively monitored by some tumor suppressive non-coding RNAs, such as miR-489 and miR-219–5p." (PMID 29547122, 2018). "Furthermore, SPIN1 was reported to be highly expressed in several types of tumors, and ectopic expression in cell lines was observed to affect cell cycle, chromatin segregation, or to induce apoptosis, cellular transformation, or tumor formation in nude mice." (PMID 25749382, 2015). "Notably, SPIN1 acts as a transcriptional coactivator of ß-catenin and T cell Factor 4 (TCF-4) enhancing their contribution to Wnt/TCF-4 pathways, which leads to tumor progression." (PMID 37055532, 2023). "This exogenous expression imbalance between pro-oncogenic SPIN1 and tumor-suppressing SPIN3 may reflect a mechanism used by TCam-2 cells to maintain tumor phenotype." (PMID 30197756, 2018). "Human SPIN1 overexpression increased the proportion of mouse NIH3T3 cells in S and G2/M phases, promoted proliferation and colony formation in vitro, and induced tumor formation in nude mice." (PMID 30197756, 2018). "Our results strongly suggest that SPIN1 is a proto-oncogene, while SPIN3 is a tumor suppressor." (PMID 30197756, 2018). "It appears that SPIN1 is pro-oncogenic and SPIN3 acts as a tumor suppressor in TCam-2 cells." (PMID 30197756, 2018). "Interestingly, CD4+ T cells and macrophages, which are the main immune cells that kill tumor cells, were not or only slightly influenced by Spindlin-1 inhibitors." (PMID 40512144, 2025). "In addition, the role of SPIN1 in NSCLC radiosensitivity in vivo was assessed by using tumour xenograft models treated with or without irradiation." (PMID 39548064, 2024).
tumor (continued). "This is the case of the Akt pathway, whose kinase activity can be increased by inhibitors of the expression of the PTEN tumor suppressor, such as miR17-92, miR-19a/b or miR-221-3p or silenced by miR-208a and miR-489, which block phosphoinositide 3-kinase (PI3K) and spindlin-1 (SPIN1), respectively." (PMID 37686073, 2023).
infection (6 papers, 2014 to 2025). The state of being infected such as from the introduction of a foreign agent such as serum, vaccine, antigenic substance or organism. "This suggests that Spindlin-1 inhibitors, while mediating anticancerogenic effects, may also suppress the humoral immune response and increase infection risk." (PMID 40512144, 2025). "In the 72 h infection group, the mRNA expression was up-regulated and the protein expression was down-regulated in 7 groups, namely the TNXB, NFIA, PROC, SPIN1, NR2C2 nuclear receptor subfamily 2 group C member 2, Carboxypeptidase D and ARHGAP11B." (PMID 36496794, 2022). "In the 72 h infection group, the mRNA expression was up-regulated and the protein expression was down-regulated in seven groups, namely the TNXB, NFIA, PROC, SPIN1, NR2C2 nuclear receptor subfamily 2 group C member 2, Carboxypeptidase D and ARHGAP11B." (PMID 36496794, 2022). "Unexpectedly, however, spin-1(ok2087) (p < 0.0001) and spin-4(ok2620) (p = 0.0062) mutant worms were more resistant to P. aeruginosa PA14 infection than the wild-type worms." (PMID 33105563, 2020).
SPIN1 also shares sentences with these, for which no sentence is quoted: triple-negative breast carcinoma (2 papers); breast tumor (1); colorectal tumors (1); erythroleukemia (1); esophageal squamous cell carcinoma (1); heart failure (1); hyperlipidemia (1); Infertility (1); leukemia (1); liver diseases (1); metastasis (1); Obesity (1); pancreas cancer (1); promyelocytic leukemia (1); sarcoma (1); viral infection (1).